IL17A (interleukin 17A)
Diseases named in the same sentence as IL17A in open-access papers (continued):
Sharing a sentence is not in itself a finding about the gene and the disease.
lupus nephritis (73 papers, 2009 to 2025). Glomerulonephritis in the context of systemic lupus erythematosus. "In children with lupus nephritis, enhanced migratory activities of IL-17A-expressing T cell subsets have been linked to enhanced Akt signaling." (PMID 35620115, 2022). "Previous reports indicated that IL-17A is associated with disease activity in patients with SLE as well as with lupus nephritis." (PMID 32183259, 2020). "IL17A polymorphism has also been reported as a risk factor for lupus nephritis." (PMID 36556060, 2022). "Indeed, lower numbers of IL-17A-producing Th17 cells in IL-23R-deficient B6/lpr mice resulted in reduced anti-DNA antibody levels and lupus nephritis." (PMID 36248812, 2022). "Study SELUNE (NCT04181762), a phase III randomized, double-blind trial, aims to investigate the efficacy and safety of secukinumab, an anti-IL-17A monoclonal antibody, in combination with the standard of care therapy in patients with active lupus nephritis." (PMID 37833861, 2023). "Immunohistochemistry of renal biopsy specimens obtained from 6 patients with lupus nephritis and 5 with IgA nephropathy was conducted to detect IL-17A-expressing CD4+Foxp3+ cells." (PMID 32317002, 2020). "In contrast to the findings presented here, several groups reported that IL-17A and the Th17 immune response have a relatively minor impact on the pathogenesis of lupus nephritis." (PMID 32183259, 2020). "The cytokine IL-17A plays an important role in the development of lupus nephritis; it is produced by T-helper 17 (Th17) cells and has powerful inflammatory properties." (PMID 32183259, 2020). "In patients with lupus nephritis, DN T-cell showed pro-inflammatory features producing IL-17A and were found in renal lesions." (PMID 31921121, 2019). "Activation of IL-23/IL-17A axis induces expansion of highly pathogenic TH17 cells, ultimately contributing to pathogenesis of lupus nephritis by enhancing immunoglobulin and complement deposition." (PMID 30524430, 2018). "Studies in cSLE have also presented an increased level of IL-17A and its correlation with SLEDAI, as well as the predominance of Th17 cells and their association with active lupus nephritis." (PMID 28380214, 2017). "Serum levels of Th1 cytokines (IFN-γ, IL-18, and IL-12p70) and Th17 cytokines (IL-17A and IL-6) were significantly elevated in lupus nephritis-IV when compared with healthy control." (PMID 27738386, 2016). "Th1 and Th17 cytokines (IL-18, IFN-γ, IL-12p70, IL-6, and IL-17A) were considerably expressed in the serum of lupus nephritis IV patients in comparison to the healthy control." (PMID 27738386, 2016). "Proinflammatory chemokines (MCP-1) and cytokines (IL-6, TNF-α), Th1 cytokines (IL-2, IFN-γ), Th2 cytokines (IL-4, IL-10), and Th17 cytokines (IL-17A) are involved in pathogenesis of lupus nephritis, and are therapeutic targets for lupus nephritis." (PMID 27846813, 2016). "Besides the increased values in serum, high levels of IL-17A have been seen mainly in lupus nephritis and SLE patients’ skin and CNS lesions." (PMID 37833861, 2023). "Thus, IL-17A-producing cells particularly DNTs have been shown to invade inflamed kidneys of lupus nephritis patients." (PMID 35620115, 2022). "CD4+Foxp3+IL-17A+ cell infiltration was found in renal biopsy specimens of active lupus nephritis." (PMID 35197962, 2021). "Finally, IL-17A-expressing CD4+Foxp3+ T cells were also detected in renal biopsy specimens of patients with active lupus nephritis." (PMID 32317002, 2020). "Finally, CD4+Foxp3+IL-17A+ cells were infiltrated into the renal biopsy specimens of patients with active lupus nephritis." (PMID 32317002, 2020). "Furthermore, IL-17A producing DN T cells have been found in the kidneys of lupus nephritis patients." (PMID 30858513, 2019). "And also in B6.lpr mice, it was recently shown that IL-17A deficiency did not affect the morphologic or functional features of lupus nephritis." (PMID 31297111, 2019).
lupus nephritis (continued). "The decrease of IL-17A may contribute to the reduced severity of lupus nephritis observed." (PMID 38886451, 2024). "For example, USP4 has been shown to interact with and deubiquitinate RORγt, promoting its function and IL-17A transcription in rheumatic heart disease; similarly, USP7 has been found to promote lupus nephritis by regulating NF-κB p65 signaling via JMJD3 stabilization." (PMID 39134949, 2024). "Not only CD4+ T cells, but also CD3+CD4−CD8− double-negative T cells were reported to be major producers of IL-17A in the kidney of lupus nephritis patients." (PMID 32183259, 2020). "In this study, an IL-17A therapeutic DNA vaccine successfully attenuated the progression of lupus nephritis in SLE model mice, indicating that IL-17A could be a good therapeutic target for SLE." (PMID 32059488, 2020). "Sole targeting of IL-17 in murine lupus nephritis models either with genetic deletion or utilizing a blocking antibody against IL-17A had no impact on the disease." (PMID 30524430, 2018). "CD4+IL-17A+ cells were detected mainly in the interstitial lesions of kidneys from both patients with lupus nephritis and those with IgA nephropathy, but the majority of the CD4+IL-17A+ cells also showed nuclear/cytoplasmic expression of Foxp3 in patients with lupus nephritis." (PMID 32317002, 2020).
lung disease (72 papers, 2005 to 2026). "IL-17A from ILC3 is recognized as a key driver of neutrophilic inflammation that play pathogenic role in lung disease." (PMID 40568586, 2025). "While a multitude of studies have addressed the role of IL-17A, -C, and -F in lung diseases, the remaining IL-17-cytokines have received little attention so far." (PMID 35883573, 2022). "The presence of IL-17A is consistent with chronic neutrophilia in a host of lung diseases, including cystic fibrosis and bacterial pneumonia." (PMID 35268581, 2022). "Rapid secretion of IL-17A and IL-22 highlights the role of ILC3s in lung diseases, as the IL-17/IL-22 axis contributes a lot to the epithelial immunity." (PMID 33718260, 2021). "IL-17A is critical in the early defense against Streptococcus pneumoniae (S. pneumoniae), as mice lacking IL-17A and IL-17RA show increased vulnerability to bacterial pathogens that incite lung diseases." (PMID 38255898, 2024). "We have investigated the activity of IL-17A in an in vitro model of alveolar basal epithelial cells (A549 cell line) cultured in the presence or absence of OLP in order to mimic the beneficial effect of a healthy diet including olive oil in lung diseases." (PMID 38999871, 2024). "Therefore, the balance of Treg and Th17 cells can be regulated by adjusting the expression of cytokines such as IL-17A, IL-6, IL-23, IL-33 and Foxp3 to achieve the goal of treating lung diseases." (PMID 37795866, 2023). "Furthermore, absence of IFNγ or of IFNγ signaling in the recipients' pulmonary parenchymal cells promoted expansion of IL-17A-producing cells, thus increasing the severity of lung disease." (PMID 23843069, 2013). "Chronic infection with P. aeruginosa appears to be associated with higher mRNA expression of these cytokines in CF airways and additional longitudinal studies are needed to support the importance of IL-23/IL-17A mediated airway inflammation in the development of CF lung disease." (PMID 21143945, 2010). "Interventional studies will be required to determine whether targeting IL-17A is therapeutically beneficial in lung diseases characterised by excessive accumulation of neutrophils." (PMID 15916703, 2005). "In the present study, we found elevated levels of both IL-17A protein and mRNA levels and also of IL-23 mRNA in sputum of clinically stable CF patients as compared to healthy controls, thus suggesting a potential role of Th17 cells in the pathophysiology of CF lung disease." (PMID 21143945, 2010). "A previous study reported a correlation between IL-17A and the degree of tissue fibrosis in systemic sclerosis and lung disease; however, no study has reported a relationship between tissue fibrosis and IL-17A in cancer." (PMID 32488650, 2021). "It has to be underlined, however, that the hypothesized antifibrotic role of IL-17A in SSc is not supported by experimental models of inflammatory/drug-induced fibrosis, in which IL-17A seems to induce fibrosis in both skin and lung disease." (PMID 32174912, 2020).
parasitemia (70 papers, 2010 to 2026). "Plasmablasts from T. cruzi-infected mice secrete IL-17, control parasitemia, and decrease plasma TNF levels in muMT-infected mice, since muMT recipients of IL-17A-deficient B cells had higher parasitemia and high levels of TNF compared to muMT recipients of WT B cells." (PMID 29209313, 2017). "The production of these inflammatory mediators suggests that IL-17a plays a role in intracellular parasite infections, as evidenced by studies on Trypanosoma cruzi infections in humans." (PMID 41310729, 2025). "IL‐17A, acknowledged as the proinflammatory component of tissues, has been recognized as a pivotal cytokine in combating parasitic infections and demonstrating diverse functionalities." (PMID 38888451, 2024). "Elevated serum IL-17A levels accompanied by increased parasitemia were found in SM patients compared to UM and controls (P < 0.0001)." (PMID 38438955, 2024). "IFN-γ and monocyte chemoattractant protein-1 (MCP-1) production induced in T. cruzi-infected infants correlated with parasitemia, whereas the plasma levels of IL-17A, IL-17F, and IL-6 were less parasite load-dependent." (PMID 38133693, 2023). "Mice treated with anti-IL-17A-depleting antibodies had similar parasitemias, clinical scores, and survival as the rat Ig control group." (PMID 37962347, 2023). "The observation of increased parasitemia in IL17A-KO mice infected by Leishmania infantum supports a role of IL17A in controlling parasitemia." (PMID 33193300, 2020). "On the other hand, the reduced production of IFN-γ, IL-6, and TNF-α cytokines in C57BL/6 IL-17A knockout (IL-17A -/-) mice infected with T. cruzi Tulahuén strain produced a more severe parasitemia and mortality, than observed in wild-type mice." (PMID 33329529, 2020). "Similar to IL-17A, IL-17E acts as a “mucosal barrier” molecule that confers immunity against parasitic infections." (PMID 32849528, 2020). "We found that the chronic patients showed correlation of plasma levels of IL-17A with parasitemia during infection, and they had significantly higher levels of IL-17A compared with the sero-negative controls." (PMID 31553732, 2019). "Between the initial visit and during the 12 months follow-up, the IL-17A levels decreased significantly after the treatment, similar to qPCR parasitemia measurements (Kruskal-Wallis test; P<0.0001)." (PMID 31553732, 2019). "We also determined a correlation between plasma cytokine concentrations and parasitemia before treatment, finding only IL-17A and IL-17F have significant positive correlations (r = 0.38; P = 0.001 and r = 0.44; P = 0.003, respectively)." (PMID 31553732, 2019). "This study provides evidence that, in addition to Th17 cells, B cells also participate in dysregulated IL-17A production and enhance chronic inflammatory responses in parasite infection." (PMID 28732522, 2017). "IL-17A−/− mice infected with T. cruzi had a lower survival rate, multiple organ failure, and sustained parasitemia compared with wild-type mice, indicating that IL-17A is crucial to leukocyte activation that are critical for parasite killing." (PMID 22545173, 2012). "Likely, the simultaneously reduced nTreg and IFN-γ (or IL-17A)-secreting CD4+ T cells may considerably explain the comparable parasitemia in WT versus RACK1 KO mice during the early phase of infection." (PMID 39024388, 2024). "Moreover, the high parasitemia in the SM group accompanied the IL-17A increase." (PMID 38438955, 2024). "Various clinical parameters, echocardiography findings, parasitemia status, brain natriuretic peptide (BNP) and troponin T (TnT) levels, and inflammatory biomarkers (IL-6, IL-10, IL-12p70, IL-17A, adiponectin, and IFN-γ) were assessed." (PMID 38109427, 2023). "To investigate if parasite burdens were associated with specific cytokines, we performed a correlation analysis comparing parasitemia and cardiac parasite burden with the TH17 cytokines IL-17A, IL-21, IL-22, and IL-23." (PMID 33547365, 2021).
parasitemia (continued). "Interestingly, B cell production of IL-17A is independent of those factors, at least in the context of parasitic infection." (PMID 33824206, 2021). "Although we could not make any clear diagnosis on whether the treated is cured or non-cured using serology and PCR, cytokine profile especially IL-17A suggested that parasite infection continued only in the non-reactive group but not in the ambiguous group." (PMID 31553732, 2019). "Patients with detectable parasitemia measured by RT-PCR in peripheral blood had a higher concentration of TNF-α, IL-1β, IL-4, and IL-6, whereas those with negative RT-PCR showed elevated levels of IL-17A." (PMID 38133693, 2023).
ischemic stroke (69 papers, 2012 to 2026). A stroke disorder caused by obstruction of blood flow to the brain, due to thrombotic (local blood clot formation) or embolic (due to a blood clot or other material traveling from another site) event. "In this study, we further explored the potential therapeutic effect of IL-17A-neutralizing monoclonal antibody (mAb) on the neurological outcome of mice with ischemic stroke and its underlying molecular mechanism of neuronal apoptosis." (PMID 33101005, 2020). "The results showed that 1-h MCAO/R 3-day-induced ischemic stroke led to a significant neuron loss (p < 0.001, n = 6 per group) in the peri-infarct region of IgG isotype and IL-17A mAb-treated mice." (PMID 33101005, 2020). "A recent study revealed that higher levels of IL-17A were associated with poorer cognitive status in subjects with depressive symptoms in ischemic stroke patients." (PMID 31686986, 2019). "The aim of our study was to investigate the association of interleukin-17A (IL-17A) polymorphisms with IL-17A serum levels and risk of ischemic stroke (IS) in a Chinese population." (PMID 29262579, 2017). "IL-17A was associated with poorer cognitive status in subjects with depressive symptoms in ischemic stroke patients." (PMID 26373740, 2015). "However, the effects of IL-17A neutralization on the neurological outcome of mice with ischemic stroke and its underlying molecular mechanism are unclear." (PMID 33101005, 2020). "IL-17A-neutralizing mAb could effectively reduce the infarct volume and neuron loss in the peri-infarct region and then improve the neurological outcomes of mice with ischemic stroke in vivo." (PMID 33101005, 2020). "First, we verified the inhibition of IL-17A expression in the brain of ischemic stroke mice by injection of IL-17A mAb by Western blot analysis." (PMID 40290135, 2025). "Secondly, the effects of the P2X7 receptor on γδT cells, another source of IL-17A, as well as other relevant cell types during ischemic stroke, remain unexplored." (PMID 40948793, 2025). "In animal models of ischemic stroke, Th17 cell and IL-17A levels are also increased in both the brain and circulation." (PMID 40948793, 2025). "In this paper, we review the mechanism of action of Th17 cells and IL-17A in ischemic stroke and the progress of research on targeted therapy." (PMID 37884768, 2024). "Immunotherapy targeting IL-17A and Th17 cells has shown good ameliorative effects in ischemic stroke mice." (PMID 37884768, 2024). "Numerous studies have suggested that in animal ischemic stroke models, Th17 cell and IL-17A levels in the brain and circulation tend to increase after infarction." (PMID 37884768, 2024). "It is important to understand the pathophysiological role of IL-17A in the acute to recovery phase of ischemic stroke and to suggest appropriate therapeutic approaches." (PMID 37884768, 2024). "It is reported that Vγ4 γδ T cells-derived IL-17A is involved in evoking the inflammatory cascade in the ischemic stroke." (PMID 37063908, 2023). "Interleukin-17A (IL-17A), an essential immune cytokine, aggravates cerebral ischemia in the acute stage of ischemic stroke by upregulating inflammatory mediators and chemokines." (PMID 37287803, 2023). "Another result revealed that the NF-κB/IL-17A signaling pathway plays an important role in EE-mediated a favorable microenvironment after ischemic stroke." (PMID 37688770, 2023). "IL-17A increases rapidly after ischemic stroke and plays a crucial role in aggravating cerebral infarction through various ways." (PMID 35663549, 2022). "Later, clinical research is needed to verify the role of the γδ T cell-IL-17a axis in patients suffering from ischemic stroke and potential mechanisms, so that to develop more effective therapies applied to clinical practice." (PMID 35432162, 2022). "Second, IL-17A promotes the activation of microglia and astrocytes cells, as well as the production of inflammatory cytokines after ischemic stroke." (PMID 35663549, 2022).